CD28 (CD28 molecule)
Diseases named in the same sentence as CD28 in open-access papers (continued):
Sharing a sentence is not in itself a finding about the gene and the disease.
pulmonary fibrosis (9 papers, 2010 to 2025). Chronic progressive interstitial lung disorder characterized by the replacement of the lung tissue by connective tissue, leading to progressive dyspnea, respiratory failure, or right heart failure. "In fact, studies with CD28‐deficient mice indicate that T cell co‐stimulation via CD28 is crucial for the development of bleomycin‐induced pulmonary fibrosis." (PMID 29721324, 2018). "Dysregulated expression of genes, including MMP8, in PBMCs of patients with idiopathic pulmonary fibrosis has been reported, and reduced CD28, ICOS, LCK, and ITK gene expression in PBMCs was associated with poor outcome in cohorts with this disorder." (PMID 29445374, 2018). "Interestingly, the reduced expression of α-Klotho, known for its anti-aging and anti-inflammatory properties, in peripheral blood CD4+ cells suggests premature aging potentially linked to decreased CD28 expression, akin to observations in pulmonary fibrosis." (PMID 39062798, 2024). "Using complementary models, we demonstrated that dual ICOS/CD28 blockade by acazicolcept decreased dermal and pulmonary fibrosis and alleviated pulmonary hypertension." (PMID 34986869, 2022). "In systemic sclerosis-induced pulmonary fibrosis, the CD28-ICOS signal is involved in Th2 effector cell differentiation in the lung." (PMID 35184642, 2022). "Some investigations have proposed that targeting the CD28-mediated co-stimulatory pathway could represent a promising therapeutic strategy for preventing pulmonary fibrosis." (PMID 40483519, 2025). "Furthermore, our study demonstrated that the concomitant blockade of both ICOS and CD28 pathways with acazicolcept leads to a significant decrease in dermal and pulmonary fibrosis in two complementary mouse models of SSc." (PMID 34986869, 2022). "In addition, and similarly to lung fibrosis, the peripheral blood of RA patients contains enlargement of both memory and CD4+CD28− T cell populations." (PMID 39062798, 2024).
acute coronary syndrome (8 papers, 2012 to 2024). Signs and symptoms related to acute ischemia of the myocardium secondary to coronary artery disease. "Furthermore, CD28− T cells are found to be upregulated in the clinical situation linked to acute coronary syndrome." (PMID 35958279, 2022). "Researchers in a recent study reported that OX40 expression was upregulated on CD4+CD28− T cells in patients with acute coronary syndrome and that the secretion of IFN-γ and TNF-α was suppressed by OX40 blockade." (PMID 28320444, 2017). "A novel finding was that circulating CD4+CD28null T cells from acute coronary syndrome patients expressed higher levels of 4-1BB costimulatory receptors compared to classical CD4+CD28+ T lymphocytes." (PMID 27617959, 2016). "At the current state there are only data available regarding the role of hHSP-60 in activation of CD4+CD28− T cells in acute coronary syndrome patients." (PMID 25834833, 2015). "The functional role and mechanism of KIRs are still elusive but a subtype of this family, KIR2DS2, was detected on the surface of CD4+CD28− T cells from RA and acute coronary syndrome patients." (PMID 25834833, 2015). "CD4+ CD28− T cells also called CD28 null cells have been reported as increased in the clinical setting of acute coronary syndrome." (PMID 25997053, 2015). "It is interesting in this context that KIR2DS4 molecule was expressed on remarkable proportion of CD4+CD28− T cell clones isolated from an acute coronary syndrome patient." (PMID 23028591, 2012). "CD4+CD28− T cells detected in acute coronary syndrome patients express enhanced levels of OX40 and 4-1BB compared to their CD28+ counterparts." (PMID 25834833, 2015).
Allergy (8 papers, 2010 to 2024). An allergy is an immune response or reaction to substances that are usually not harmful. "In both allergy groups, the expression of CD28 was statistically significantly increased compared to the control group, supported by two generations of child clusters." (PMID 32698761, 2020). "Under allergen stimulation, CD28 expression increased significantly in R and AR, and blockade of CD28 decreased the Th2 cytokine production, indicating the involvement of CD28 in Th2 cell activation in allergy." (PMID 21356099, 2011). "This was important because CD28 is also expressed by the cells responsible for allergy and the fact that the adverse reactions were immediate, relates to the release of preformed cytokines in granules of allergy-mediating immune cells." (PMID 21042496, 2010). "The suggestive DMRs in this study highlight immune dysfunction through the enrichment of not just immune pathways in general, but to those important to allergic disease, including IL-4 signaling, NFAT regulation of immune response, CD28 signaling in Th cells, and so on." (PMID 26642056, 2015).
latent infection (8 papers, 2009 to 2024). "The clonal expansions of CD28+CD57+ cells and CD8+CD28− effector cells are both closely associated with CMV infection, strongly suspected to be a cause of lifelong latent infection and immune erosion in late life." (PMID 28721254, 2015). "We also quantified post-integration latent infection by stimulating T-cells with anti CD3/CD28 and IL-7 stimulation in the presence of L8." (PMID 26362311, 2015). "CD80 and CD86 interact on APC and CD28 on T cells as costimulatory signals for the activation of T cells, are key players in anti-viral humoral and cellular immune responses, and play a critical role in the control of chronic and latent infections." (PMID 38674902, 2024). "The EGFP- cells were then activated with anti-CD3/anti-CD28/IL-7 to reactivate latent infection." (PMID 27383184, 2016). "The finding that the CMV-specific CD8 T cell phenotype in elderly individuals is similar to the predominant phenotype of CD8 T cells as a whole, suggest that latent infection with CMV can be considered as a major force contributing to the differentiation of CD8 T cells into CD27- CD28- cells." (PMID 19715573, 2009).
lupus nephritis (8 papers, 2015 to 2024). Glomerulonephritis in the context of systemic lupus erythematosus. "Reduction of IFNγ levels could improve the outcome of lupus nephritis by inactivating B7/CD28 signalling pathway, which results in a reduction in ANA autoantibodies, IL-4 and IFNγ levels." (PMID 34386197, 2020). "The aim of this study is to inquire whether the quantitative changes of CD3+CD8+CD28− T lymphocytes subpopulation are related to the clinical status of patients with lupus nephritis." (PMID 27446964, 2016). "Additionally, inhibiting the CD80-CD28-mediated signaling pathway via specific RNAi and antibodies to block the interaction between CD28 and B7 reduced immune cell activation and reversed the damage in a pathological lupus nephritis model." (PMID 38524638, 2024). "A recent study on lupus nephritis provided data supporting a theory that IL-15 could be a major factor for enhancement of cytotoxic activity of CD4-positive CD28-negative T cells." (PMID 37108157, 2023).
mesothelioma (8 papers, 2014 to 2023). A usually malignant and aggressive neoplasm of the mesothelium which is often associated with exposure to asbestos. "In vitro, human CAR T cells prepared with either high-affinity 4m5.3 or lower-affinity E2 scFv-based CARs exhibited potent cytotoxicity against amph-FITC-tagged MSTO-211H human mesothelioma tumour cells, irrespective of the use of CD28 or 4-1BB co-stimulatory domains." (PMID 37291434, 2023). "These CAR T cells were expanded for seven days with CD3/CD28 beads and IL-2 in the presence or absence of CAL-101 or AKTi before transfer into mice bearing subcutaneous M108 mesothelioma tumor." (PMID 29033940, 2017).
parasitemia (8 papers, 2011 to 2020). "A published report has shown that low level parasitemia is retained in CD28 knockout mice infected with malaria, suggesting that parasite control occurs via additional immune processes." (PMID 31979279, 2020). "The effects of the CD28 deficit resulted in an inability of these mice to clear parasitemia to sub-patent levels or control re-infections." (PMID 30631323, 2018). "Given that CD28-deficient mice appeared to be resistant to T. gondii infection, CD28-independent responses were investigated for their role in T-cell activation to parasite infection." (PMID 21687650, 2011). "Mice knockout for CD28 presented high parasitemia and mortality." (PMID 25197170, 2014). "Considering the paucity of available data, what are the roles of CD209, CD28 and STAT6 gene polymorphisms, either individually or in combination, with malaria infection among children, and how are they associated with markers of disease severity (age, anemia and parasitemia)?" (PMID 31979279, 2020). "Because generation of classic memory T and B cell responses to Pc infection requires CD28 signaling, it is intriguing how CD28KO mice survive acute infection and maintain relatively low levels of chronic parasitemia." (PMID 30148845, 2018). "Studies using P. chabaudi malaria have revealed that antibody blockade of CD80 binding to CD28 did not significantly affect the clearance of parasitemia." (PMID 30631323, 2018). "In C57BL/6 (Cd28+/+) mice, Pc-iRBCs were no longer detected by microscopic examination after clearance of acute parasitemia." (PMID 30148845, 2018). "No change in N67 parasitemia was observed between anti-CD28 treated and untreated groups; however, better survival was observed in infected mice treated with 200 μg anti-CD28 antibody." (PMID 30327482, 2018). "However, mice lacking the costimulatory receptor CD28 (CD28KO) maintain chronic parasitemia at low levels and do not succumb to infection, suggesting that other immune responses contribute to parasite control." (PMID 30148845, 2018). "However, when infected with the low virulent Sylvio X10/4 trypanosome strain CD28-KO mice exhibited resistant phenotype, with no parasitemia or mortality." (PMID 25197170, 2014).
uveitis (8 papers, 2010 to 2023). An inflammatory process affecting a part of or the entire uvea. "Cluster of differentiation 4 (CD4)+ T cells from BD patients with active uveitis were co-cultured with anti-cluster of differentiation 3/cluster of differentiation 28 (CD3/CD28) antibodies in the presence of infliximab." (PMID 22546542, 2012). "In vitro, CsA significantly inhibited the production of IL-17 and IFN-γ by PBMCs activated with anti-CD3 and anti-CD28 antibodies or phorbol 12-myristate,13-acetate and ionomycin in BD patients with active uveitis." (PMID 20508866, 2010). "A small number of studies in humans treated with abatacept, a US Food and Drug Administration (FDA) approved biologic targeting T-cell costimulation through interruption of the B7/CD28 interaction, suggest similar mechanisms are relevant in patients with uveitis." (PMID 36976157, 2023). "Combined inhibition of CD28 and inducible T cell costimulator (ICOS) pathways with acazicolcept (ALPN-101) represents a potential new treatment for uveitis." (PMID 36976157, 2023). "CD4+ T cells from BD patients with active uveitis were co-cultured with rIL-2, anti-human CD3 Ab, and anti-human CD28 Ab in the presence of infliximab for 48 hours." (PMID 22546542, 2012). "Together, these data show that in eyes with uveitis the majority of CD4+, and to a lesser extent CD8+, T cells express the costimulatory receptors CD28 and ICOS, and treatment with acazicolcept provides significant blockade of these receptors on ocular infiltrating T cells." (PMID 36976157, 2023).
end-stage renal disease (7 papers, 2013 to 2025). "Chronic kidney disease acts in a similar way, as a cause of T-cell abnormalities, with a shift to the immunosenescent phenotype, including a reduction in CD45RA+CD28+ naïve subsets and an increase in CD28null cells." (PMID 33804135, 2021). "Experimental data showed that isolated CD28+ T cells obtained from end-stage renal disease patients exposed to allostimulation in the presence of belatacept differentiated into CD28− T cells producing high amounts of IFN-γ and were able to mediate allogeneic response." (PMID 30729139, 2019). "Proinflammatory CD4+ T cells without the costimulatory molecule CD28 (CD4+CD28null T cells) are expanded in patients with end-stage renal disease (ESRD) and associated with atherosclerotic vascular events (AVE)." (PMID 24288592, 2013). "End-stage renal disease (ESRD) and solid organ transplants have both been associated with an increase of CD28- T cells (and therefore a decrease of CD28+ T cells) which could account for the loss of CD28+ T cells in our data." (PMID 38993862, 2023). "A reduction in CD28 expression both in CD4 and CD8 subpopulations was also found in patients with end stage renal disease." (PMID 36320075, 2022). "Furthermore, centenarians and chronic kidney disease patients assigned to cluster 3, showed a high frequency of CD8+CD28− T cells as well as memory switched CD19+ cells." (PMID 40308557, 2025).
experimental autoimmune encephalomyelitis (7 papers, 2016 to 2024). An autoimmune demyelinating disease of the central nervous system that is produced experimentally in animals by the injection of homogenized brain or spinal cord in Freund's adjuvant. "For example, methylation changes in CD28, a gene crucial for development of experimental autoimmune encephalomyelitis in mice, was less methylated in MS patients as compared to controls but was more methylated in 2nd trimester pregnant as compared to non-pregnant women." (PMID 34605719, 2022). "In experimental autoimmune encephalomyelitis, CD8+CD28- Tregs inhibited the secretion of IFN-g by myelin oligodendrocyte glycoprotein-specific CD4+ T cells." (PMID 34335631, 2021). "The CD28 PYAP ICD, which is necessary for ARS2 upregulation, was previously shown to be important for in vivo T-cell functions in models of allergic airway inflammation and experimental autoimmune encephalomyelitis, both of which are driven primarily by CD4+ T cells." (PMID 38233562, 2024).
malaria (7 papers, 2016 to 2020). Malaria is a serious and sometimes fatal disease caused by a parasite that commonly infects a certain type of mosquito which feeds on humans. "On the other hand, we report a low genotypic frequency of the CD28 (rs35593994) homozygote recessive (A/A) variant in the malaria group, though statistically insignificant, implying that this variant possibly has a protective effect against infection." (PMID 31979279, 2020). "Studies have shown the significant co-stimulation of CD28 in protective immune responses against various diseases, including malaria, with its polymorphisms also showing interethnic delineation mediating disease outcome." (PMID 31979279, 2020). "CD28 was found to be crucial for development of both polyclonal as well as specific antibody responses against malaria, as mice deficient in CD28 had a severe deficit in Ig-production by B cells by day 7 post-infection with P. chabaudi compared to WT mice." (PMID 30631323, 2018). "Another study showed that in JH-/- mice which lack B cells, a deficiency of CD28 resulted in diminished clearance of P. chabaudi parasitemia, demonstrating that CD28 is crucial to both humoral and cell-mediated immunity to malaria." (PMID 30631323, 2018). "We also determined if symptomatic malaria may be associated with the biological aging of T cells, by measuring senescent markers using CD28 and CD57 and comparing the proportions with the asymptomatic and healthy groups." (PMID 31316497, 2019). "Therefore, CD28 genetic polymorphisms may also serve an important role in the varying susceptibility to malaria." (PMID 31979279, 2020). "This study demonstrates that CD28 deficiency results in the generation of germinal-center independent IgM+ experienced B cells and the production of protective IgM during experimental malaria, providing evidence for an additional mechanism by which the immune system controls Plasmodium infection." (PMID 30148845, 2018). "Our results show significant differences in genotypic frequencies between malaria and control groups for CD28 (rs35593994; p = 0.0001) and CD209 (rs4804803; p = 0.0001) but not STAT6 (rs3024974; p = 0.30) gene polymorphisms." (PMID 31979279, 2020). "The linkage disequilibrium (LD) analysis showed the strongest association between CD28 (rs35593994) and CD209 (rs4804803) gene polymorphisms in the malaria group (0.77; p = 0.0022)." (PMID 31979279, 2020). "To answer these questions, we evaluated the genetic variability of CD209 (rs4804803), CD28 (rs35593994) and STAT6 (rs3024974) single nucleotide polymorphisms among malaria-infected children in Nigeria and extrapolated any association with markers of infection." (PMID 31979279, 2020). "The genotypic frequencies of STAT6, CD28 and CD209 gene promoter polymorphisms in malaria patients were compared to the control group with logistic regression analysis." (PMID 31979279, 2020). "We genotyped blood samples collected from a total of 561 individuals (231 malaria-infected patients and 330 uninfected, control individuals) for STAT6 (rs3024974), CD28 (rs35593994) and CD209 (rs4804803) gene polymorphisms using Taqman SNP genotyping assays." (PMID 31979279, 2020). "We found that CD8+CD28+GzmB+ T cells were enriched in malaria patients compared to healthy controls and patients suffering from AIH, PBC, PSC or chronic HBV infection." (PMID 30483269, 2018). "Our data suggest that CD209 (rs4804803) is a susceptibility factor for clinical malaria that also influences disease pathogenesis, but not CD28 (rs35593994) or STAT6 (rs3024974)." (PMID 31979279, 2020). "Also, the percentage expression of CD57 on CD28- CD8+ T cells was significantly increased in children with symptomatic malaria compared to those with asymptomatic malaria (p = 0.0175) or healthy controls (p = 0.0147)." (PMID 31316497, 2019).
malaria (continued). "In our study, we observed that both the proportion of CD28- T cells that express CD57 were expanded in the symptomatic malaria group, suggesting that T cell aging in falciparum infections is more similar to that observed during CMV infections than in HIV infections." (PMID 31316497, 2019). "Though we found a notable diversity in CD28 gene polymorphism, whereby the heterozygous variant was most common among malaria patients, and the homozygous dominant was most common among controls, this does not appear to be a factor in malaria pathogenesis." (PMID 31979279, 2020). "However, it is not impossible that STAT6 (rs3024974) and CD28 (rs35593994) polymorphisms may mediate malaria pathogenesis through a different mechanism not examined in this study." (PMID 31979279, 2020). "In this study, we phenotypically characterized the expression of T cell inhibitory(PD-1, CTLA-4) and senescent markers (CD28(-), CD57) from children with symptomatic malaria, asymptomatic malaria and healthy controls using flow cytometry." (PMID 31316497, 2019). "We characterized the expression of PD-1, CTLA-4, CD28 and CD57 markers in children with symptomatic malaria, asymptomatic malaria and healthy controls." (PMID 31316497, 2019). "This study, along with studies on the role of CD28, indicate that CD86 ligation of CD28 is essential for protective humoral immunity to malaria, while cell-mediated immunity also requires CD28 ligation." (PMID 30631323, 2018). "Thus, CD28 may be involved in the immune response against malaria." (PMID 27255376, 2016).